INS (insulin)
Diseases named in the same sentence as INS in open-access papers (continued):
Sharing a sentence is not in itself a finding about the gene and the disease.
diabetes (continued). "Moreover, the increase in body weight related to physical inactivity, high-calorie diets and decreased insulin sensitivity during pregnancy might also result in a higher risk of diabetes in later life." (PMID 37308533, 2023). "Experimental models of insulinopenic, such as streptozotocin-induced, diabetes indicated that insulin deficiency increases the activity of circulating dopamine β-hydroxylase (which converts dopamine into noradrenaline), and the administration of insulin significantly reduces the enzymatic activity." (PMID 38001993, 2023). "The protective actions of artichoke extract on the pancreatic β-cells and enhancement of their regeneration, in addition to its stimulatory effects on insulin release from cells that survived damage by the diabetes-inducing agent, may cause of the rise in serum insulin and C-peptide levels." (PMID 37163198, 2023). "As well as statins, the influence of insulin on the length of telomeres cannot be generalized because there is evidence that it can lead to telomere shortening, but also that it can have a protective effect on telomeres; while diabetes is undoubtedly associated with telomere shortening." (PMID 37759609, 2023). "Diabetes mellitus (DM) refers to a collection of metabolic illnesses associated with high plasma glucose concentrations as a result of defective insulin secretion and/ or insulin action." (PMID 38357182, 2023). "Diabetes-related dementia is thought to be caused by various factors, including insulin insufficiency, insulin resistance, hyperglycemia, vascular abnormalities, reduced synaptic plasticity, impaired insulin signaling, and oxidative stress in the central nervous system (CNS)." (PMID 37081849, 2023). "Diabetes mellitus (DM) comprises a range of metabolic disorders characterized by high blood glucose levels caused by defects in insulin release, insulin action, or both." (PMID 37513684, 2023). "There have been several reports suggesting that the SARS-CoV-2 might directly cause diabetes, and some have suggested that the virus might destroy insulin producing β cells directly or indirectly by infecting adipose cells, which produce inflammatory adipokines and enhance insulin resistance." (PMID 36857969, 2023). "Structural brain changes in obesity, such as reduced hippocampal and gray matter volume, have been linked to impaired glucose and insulin regulation, suggesting that improvement in diabetes and glucose regulation might also be associated with cognitive improvement after bariatric surgery." (PMID 37252738, 2023). "Diabetes mellitus (DM) is a metabolic disease characterized by hyperglycemia, which is caused by defective or impaired biological action of insulin secretion." (PMID 38027005, 2023). "Moreover, rs849334 of JAZF‐1 is significantly associated with insulin clearance, which could predict the progression of diabetes." (PMID 36734198, 2023). "In this sense, higher levels of BCFAs were observed in insulin-resistant and prediabetic individuals; therefore, that inulin and polyphenols had the capacity to reduce levels of Parabacteroides and Coproccus and decrease levels of BCFAs and the risk of diabetes." (PMID 37764662, 2023). "Type II diabetes mellitus (T2DM) is the most prevalent form of DM (90%), and it is mainly caused by the combination of two factors: peripheral tissue resistance to insulin and insufficient insulin secretion by pancreatic β cells." (PMID 36830792, 2023). "Diabetes mellitus (DM), currently affecting more than 537 million people worldwide is a chronic disease characterized by impaired glucose metabolism resulting from a defect in insulin secretion, action, or both due to the loss or dysfunction of pancreatic β cells." (PMID 37349801, 2023).
diabetes (continued). "Accumulating epidemiological and biochemical evidence suggests that insulin resistance in the brain leads to altered gene expression profiles in the hippocampus and prefrontal cortex of rats, suggesting an association between type 2 diabetes mellitus and Alzheimer’s dementia." (PMID 36923118, 2023). "Milk and dairy products are strong insulin secretagogues, as their intake causes acute hyperinsulinaemia, and they also contain bioactive peptides, calcium and B-complex vitamins, which support regulation of the microbiome and the metabolic control of diabetes." (PMID 37511996, 2023). "In particular, diabetes patients treated with insulin may be at the highest risk." (PMID 36765354, 2023). "Hypermethylation of ABCG1 results in a decrease in gene expression, which is associated with cholesterol metabolism disorders, impaired insulin secretion, and accelerated foam cell formation, and may contribute to type 2 diabetes mellitus, metabolic syndrome, and atherosclerosis CVDs." (PMID 37507725, 2023). "Nonetheless, caution should be exercised when using metformin in different patient populations who may be more susceptible to hypoglycemia, such as individuals with diabetes who are receiving insulin or sulfonylurea and/or those with renal and hepatic impairment." (PMID 37583905, 2023). "Diabetes mellitus (DM) portrayed by hyperglycemia, is a metabolic disorder caused by insufficient insulin production, insufficient insulin activity, or both." (PMID 37394484, 2023). "Thus, the proband in family C diagnosed with diabetes at 7 years old and had weakened insulin secretory capacity may be associated with low birth weight." (PMID 37711893, 2023). "A more permeable intestine favors the translocation of LPS into the bloodstream (metabolic endotoxemia), leading to insulin resistance, adipose tissue inflammation, and tissue infiltration of monocytes/macrophages, which increase the risk of diseases such as hepatic steatosis, obesity, and diabetes." (PMID 37156688, 2023). "Diabetes mellitus (DM) is a chronic disease with disorders of sugar, lipid and protein metabolism due to relative or absolute deficiency of insulin secretion." (PMID 37667364, 2023). "Diabetes mellitus (DM) is a systemic disease which occurs as a result of insulin deficiency or resistance of tissues to insulin and progresses with hyperglycemia." (PMID 37434133, 2023). "Further, a combination of insulin and vitamin‐C may impede blood vessel damage caused by diabetes." (PMID 37970378, 2023). "Diabetes mellitus (DM) is the most prevalent metabolic disorder caused by the inability of the pancreas to secrete insulin adequately or the body's inability to use insulin effectively." (PMID 37790847, 2023). "Then, vitamin D deficiency may alter pancreatic insulin secretion, peripheral insulin resistance, persistence of systemic “sterile” inflammation and immune activation, which increase the risk of the development of diabetes and its complications." (PMID 37845735, 2023). "Moreover, butyrate improves insulin sensitivity and reduces the risk of diabetes." (PMID 36301817, 2022). "However, weight gain, particularly visceral fat accumulation, could increase impaired insulin signaling, leading to insulin resistance and increasing the risk of progression from prediabetes to diabetes." (PMID 36277718, 2022). "Diabetes mellitus (DM) is a disorder caused by the decreased production of insulin or the decreased ability to use the produced insulin, which is a polypeptide hormone produced by the pancreatic cells." (PMID 36354609, 2022). "Diabetes Mellitus (DM) is an endocrine, metabolic disease characterized by either insulin resistance or partial/complete deficiency in pancreatic insulin secretion, resulting in persistently elevated blood glucose levels." (PMID 35767208, 2022).
diabetes (continued). "These correlations not only highlight that long illness or using insulin may heighten more severe diabetes and a higher risk of complications but also suggest that negative emotion may lead to reduced willingness and worse adherence to treatment, poorer glycemic control, and then exacerbating DR." (PMID 36187629, 2022). "Additionally, advanced glycation end products (AGEs), vascular endothelial dysfunction, dysglycemia, insulin dysregulation, and neuroinflammation may be involved in the pathogenesis of diabetes-associated cognitive decline." (PMID 35682821, 2022). "However, patients with type 1 diabetes, who have a low endogenous insulin level, may experience more glucose fluctuation, thus making the patient more susceptible to reduced quality of life and complications of diabetes." (PMID 35229479, 2022). "Diabetes mellitus (DM) is a metabolic disease caused by improper insulin secretion leading to hyperglycemia." (PMID 36080496, 2022). "The largest cluster “diabetes” mainly occurs as a cause and its 10 most frequent effects are death (n=7446), fear (n=4836), sick (n=2799), neuropathy (n=2477), hypoglycemia (n=2062), anger (n=1908), suffer (n=1808), insulin (n=1605), overweight (n=1506), and reduce weight (n=1487)." (PMID 35852829, 2022). "Higher pro-NT at the baseline predicted reduced insulin sensitivity (i.e., eIS) at 10-year follow-up (r = −0.77, p < 0.001), and this association persisted significant after adjusting for sex, age, BMI and diabetes’ duration, all considered at the follow up (p = 0.018)." (PMID 34455471, 2022). "However, in the present validation study, we confirmed that a simple model consisting of two clinical variables (history of stroke and diabetes treated with insulin) and NT-proBNP level successfully predicted the risk of stroke in HFrEF patients without AF (Structured Graphical Abstract)." (PMID 36017729, 2022). "The main medication of the diabetes is the insulin; the active form is the insulin monomer, which is an instable molecule, because the long storage time, or the high temperature, can cause the monomer insulin to adapt an alternative fold, rich in β-sheets, which is pharmaceutically inactive." (PMID 35056780, 2022). "While it was initially proposed that hyperglucagonemia in diabetes results from a loss of insulin inhibitory control on alpha-cell glucagon secretion, an alternative hypothesis is that alpha-cell number and secretory capacity is increased as a compensatory mechanism to enhance beta-cell function." (PMID 35957816, 2022). "Diabetes mellitus (DM) is a metabolic disorder marked by a persistently high blood glucose level over a prolonged period of time linked to either defects in insulin secretion, insulin action, or both." (PMID 35646765, 2022). "Diabetes mellitus (DM) is a chronic metabolic disease caused by insufficient insulin production, cellular insulin resistance, or both." (PMID 36143273, 2022). "Additionally, the effect of SB on insulin sensitivity in this population cannot be ignored, which may indicate that prolonged exposure to SB increases the risk of diabetes in this population." (PMID 36554675, 2022). "The reason is probably linked to the use of insulin alone that reflects less adherence resulting in deterioration in kidney function, decline β-cell function or increase insulin resistance over time which is associated with poor plasma glucose control and higher risk of severe diabetes." (PMID 35114950, 2022). "Diabetes mellitus (DM), which is caused by absolute or relative insulin deficiency and reduced sensitivity of target cells to insulin, is a common metabolic disease with significant health, social, and economic consequences." (PMID 35422046, 2022). "Diabetes mellitus (DM) is a group of metabolic disorders characterized by hyperglycemia caused by abnormalities in the process of insulin secretion, insulin performance, or both." (PMID 35186344, 2022).
diabetes (continued). "Furthermore, insulin is a powerful mitogen and survival factor for virtually all cell types, providing a potential mechanism for how diabetes may be associated with cancer." (PMID 34897573, 2022). "Diabetes mellitus (DM) is a disorder of carbohydrate, fat, and protein metabolism caused by either insufficient insulin secretion or dysfunctional insulin use." (PMID 35606800, 2022). "Diabetes mellitus (DM) is caused by a patient’s genetic background and environmental factors and develops when insulin secretion impairment and insulin resistance are intertwined." (PMID 36292936, 2022). "Diabetes Mellitus (DM) characterized by hyperglycemia is a systemic metabolic disease, which caused by insufficient insulin secretion and/or insulin resistance." (PMID 35383148, 2022). "In addition, since both β-cell dysfunction and insulin resistance contribute to the pathogenesis of diabetes, it would be insightful to investigate if physical activity is associated with both improved β-cell function and insulin sensitivity in the African populations." (PMID 35992098, 2022). "Additionally, PD is associated with diabetes prevalence, and tauopathy and mitochondrial dysfunction are pathophysiological mechanisms potentially shared between PD and diabetes, reducing biosynthesis and secretion of dopamine and insulin, respectively." (PMID 35897635, 2022). "Diabetes mellitus (DM) is a prodigious chronic disorder that results from absolute/relative loss of insulin (type-1 DM) or impaired insulin action and signal transduction (T2DM)." (PMID 35878267, 2022). "However, the mechanisms underlying diabetes manifestation for other heterozygous INS mutations still remain unknown." (PMID 35955956, 2022). "Diabetes mellitus is clinically categorized as type I diabetes, type II diabetes, gestational diabetes mellitus and other specific types of diabetes due to other causes such as genetic defects in b-cell function, genetic defects in insulin action and diseases of the exocrine pancreas." (PMID 35655687, 2022). "In addition, we observed a significant mediation of the association by changes in HOMA‐IR, indicating that changes in insulin sensitivity might be a potential mechanism underlying the association between glucose variabilities and diabetes risks." (PMID 35170854, 2022). "Individuals with heterozygous mutations are normoglycemic with the sufficient sensibility to insulin in the early stages, however, over time, typically occurring before the 25 years old, individuals with HNF1Apatohenic variants acquire an impaired glucose tolerance, and ultimately diabetes." (PMID 36361703, 2022). "While suggesting that insulin treatment improves the deficient immune cell migration in diabetes, it also may indicate pro-inflammatory effects due to leukocyte recruitment, although this study did not use a vehicle treatment control to compare with the insulin treated group." (PMID 35273609, 2022). "Diabetes mellitus (DM) is an increasingly common metabolic disorder characterised by complete or relative deficiencies of insulin secretion and action, that culminates in chronic hyperglycaemia." (PMID 35239729, 2022). "Furthermore, hypoglycemia was a common complication in diabetes and intensive HbA1c targets could increase the risk of hypoglycemia, especially for those treated with insulin." (PMID 35841094, 2022). "However, insulin, insulin mimics, or orthosteric InsR activators may increase the risk of hypoglycemia in patients with diabetes, potentially leading to worse glycemic control in patients." (PMID 35502441, 2022). "Diabetes mellitus (DM) characterized by hyperglycemia, caused by insufficient insulin secretion or insulin resistance, is a group of chronic metabolic diseases." (PMID 35370989, 2022).
diabetes (continued). "These latter devices are not recommended in patients on peritoneal dialysis, in which the osmotic agent icodextrin, a widely used glucose polymer, may cause falsely elevated glucose readings and improper insulin administration in patients with diabetes 104,105." (PMID 34976197, 2022). "In underweight/normal-weight categories, insulin secretion deficiency and insulin resistance may have a respectively higher and lower burden than in obese with diabetes, and an early failure of β-cells may result in appearance of diabetes at much lower insulin resistance." (PMID 36614099, 2022). "Furthermore, studies indicated that duration of diabetes, insulin use which might be associated with pain of multiple injections, are linked with poor HRQoL." (PMID 35180266, 2022). "Studies have shown that an insulin secretory defect is commonly observed due to interactive associations with age-related factors, such as impaired beta-cell compensation, adiposity, sarcopenia and decreased physical inactivity, which increases the risk of diabetes among elderly people." (PMID 36554905, 2022). "The rising prevalence of diabetes is due to several circumstances, such as oxidative stress caused by the free radical generation that may cause β-cells in the pancreas to malfunction, decreased glucose tolerance, and insulin resistance." (PMID 35214895, 2022). "Adipose tissue plays a central role in modulating lipid metabolism, insulin sensitivity, and glucose homeostasis, and differences between males and females have been described in these actions, influencing their predisposition to diabetes and associated metabolic disorders." (PMID 35807162, 2022). "Diabetes mellitus (DM), characterized by hyperglycemia, is caused by a relative or absolute deficiency of insulin in the body." (PMID 35898453, 2022). "Type 2 diabetes mellitus (T2DM) accounts for almost 90% of DM that caused by a combination of resistance to insulin action and an inadequate compensatory insulin secretory response." (PMID 35703920, 2022). "Diabetes and insulin levels may increase the risk of postmenopausal breast cancer." (PMID 34406178, 2022). "Such individuals might be characterized by higher body fat percentage, visceral fat and insulin levels, increased adipocyte size, and predisposition to type 2 diabetes mellitus (T2DM), hyperlipidemia, and cardiovascular diseases compared with patients with a similar BMI." (PMID 35967768, 2022). "Indeed, defective insulin secretion is the cause of all forms of diabetes." (PMID 35185804, 2022). "Diabetes mellitus (DM) is associated with reduced serum concentrations of melatonin in diabetic Goto-Kakizaki rats, despite increased insulin levels in these animals." (PMID 36337190, 2022). "Indeed, hepatic insulin resistance (IR) is the main condition associated with non-insulin-dependent diabetes mellitus which can impair insulin sensitivity in other insulin-dependent tissues such as muscle and adipose tissue, which absorb glucose from plasma during the postprandial phase." (PMID 35883786, 2022). "The metabolic disorder known as diabetes mellitus (DM) has several different causes, distinguish by recurring hyperglycemia developing from inadequate insulin secretion, insulin action, or both." (PMID 36312660, 2022). "Diabetes mellitus (DM), usually referred to as diabetes, is a chronic lifelong disorder caused by reduced pancreatic production of insulin or the inefficiency of the generated insulin, referred to as insulin resistance." (PMID 35627115, 2022). "A correlation such as that between BCr and Glu/BCr and SCr and Glu/SCr could result from predispositions to diabetes, as the ability to convert inorganic chromium into a useable organic form (organic chromium) that activates insulin is reduced in people predisposed to diabetes." (PMID 36278758, 2022). "Diabetes mellitus (DM) is a chronic metabolic disorder caused by an absolute or relative deficiency of insulin." (PMID 35357353, 2022).